CD4 (CD4 molecule)
Diseases named in the same sentence as CD4 in open-access papers (continued):
Sharing a sentence is not in itself a finding about the gene and the disease.
cancer (continued). "we found that the immune signatures (CD8+ T cells, CD4+ T cell, Macrophage, Neutrophil and Dendritic cell) showed significantly higher enrichment levels in TTN-wildtype than in TTN- mutated cancers in LIHC (P < 0.01)." (PMID 33861762, 2021). "An opposite effect was found in T15M CD4+ T cells continuously cultured with cancer cells from day 15 to day 18 (T18+M)." (PMID 34439305, 2021). "We found that low-dose dexamethasone (0.1 mg/kg) not only inhibited the expression of PD-L1 and IDO1 of cancer cell simultaneously, but also reduced the expression of PD-L1 on CD4+ lymphocytes." (PMID 34175886, 2021). "The link between RNMT expression and TOP-RNA expression is robust, being present in naïve and activated mouse CD4 T cells as well as human cancer cells." (PMID 34125914, 2021). "A number of important outstanding questions remain regarding the biology and regulation of cytotoxic CD4+ T cells in cancer patients." (PMID 34910940, 2021). "CD4 T cell responses are essential in the cancer immune cycle, and both significantly influence the clinical outcome." (PMID 35154072, 2021). "In fact, CD4+ memory T cells and CD8+ T cells have been previously reported to be associated with a better survival of various malignant tumors." (PMID 34899849, 2021). "PSGL-1, primarily known for its role in cellular migration, has also been shown to function as a negative regulator of CD4+ T cells in numerous disease settings including cancer." (PMID 33708224, 2021). "The therapeutic action of the anti-CD4-depleting antibody in cancer, in particular via reduction in Tregs, is well known." (PMID 34493727, 2021). "CD4+ and CD8+ T cell responses are part of the cancer immune cycle, which significantly influence the clinical treatment outcome, while the phenotype of T cell exhaustion usually occurs in both CD4+ and CD8+ T cell populations." (PMID 34858817, 2021). "IL-6 secreted by cancer cells impaired the IL-12p70 secretion from DCs, which in turn had an effect on the differentiation of CD4+ T cells." (PMID 34671021, 2021). "Evidence from mouse models and cancer patients reveal that various CD4+ T cell subsets play an antagonistic role in the antitumor immune response." (PMID 33546283, 2021). "Increasing evidence shows that some immune cells (like Neutrophils, Macrophage M2, T regulatory cell) can stimulate, while some (like Macrophage M1, CD8+ T cell and Th1 CD4+ T cell) can inhibit cancer growth." (PMID 34368124, 2021). "CD4+CD45RO+ T cells in the lesional blood highly expressed genes relating to cancer progression and CTCL pathogenesis: RGS1, RDH10, HES1, DNAH9, ANK2, and SGK1 16–25." (PMID 34608214, 2021). "Among CD4+ T cells, the percentage of Treg cells is higher in the blood of cancer patients compared to that of healthy individuals." (PMID 33809974, 2021). "The global transcriptomic analysis revealed that in CD4+ T cells co-cultured with MDA-MB-231 cancer cells (T15M), 3564 genes were upregulated and 1250 genes exhibited reduced expression levels when compared to CD4+ T cells stimulated for 12 days (T12)." (PMID 34439305, 2021). "ASF1B was associated with M2 macrophages in 7 cancers, resting Mast cells and activated NK cells in 6 cancers, M0 and M1 macrophages in 7 cancers, T follicular helper cells in 11 cancers, and resting memory CD4+ T cells in 10 cancers." (PMID 34568067, 2021). "Our data show that the iPSC-cancer vaccine significantly decreased the CD4+CD25+FOXP3+ Treg population in TDLN and spleen, reversing the immune-suppressive microenvironment in mice injected with cancer cells." (PMID 33961792, 2021). "More studies on the presence and function of CD4+ CTLs within the TME are needed for identifying the exact impact of this population in human cancer." (PMID 33546283, 2021). "The densities of CD4+ and CD4+Foxp3+ T-cells in the radiation group were statistically higher than the untreated group in carcinoma and stromal areas (p = 0.0343, p = 0.0173)." (PMID 34647108, 2021).
cancer (continued). "In this study, we have illustrated that the densities of CD4+ T-cells and CD8+ T-cells in carcinoma and stromal areas, and CD4+Foxp3+ T-cells in the carcinoma area of the brain metastases were positively correlated with OS." (PMID 34647108, 2021). "In fact, the density of CD4+ and CD4+Foxp3+ T-cells in the radiation group was statistically higher than the untreated group in both areas of the carcinoma and the stroma." (PMID 34647108, 2021). "Carcinomas evade the host immune system by negatively modulating CD4+ and CD8+ T effector lymphocytes through forkhead box protein 3 (FOXP3) positive T regulatory cells’ increased activity." (PMID 34539667, 2021). "The density of CD4+ T-cells, CD8+ T-cells, and CD4+ Foxp3-positive (Foxp3+) T-cells were statistically higher in both carcinoma and stromal areas in the primary specimens when compared with matched brain metastases (p < 0.0001, respectively)." (PMID 34647108, 2021). "The CD4+ cell was known to be correlated with poor prognosis compared with CD8+ cells in patients with cancer." (PMID 33123469, 2020). "The majority of TILs in cancer are of the T-cell phenotype, which includes CD4+ (helper cells) and CD8+ (cytotoxic cells) lymphocytes." (PMID 32222891, 2020). "We have provided herein a comprehensive view of the role of CD4 T cell immunity against TERT in cancer." (PMID 32630460, 2020). "Our laboratory was the first to report that such biased signaling is also used by chemokines to direct the biological properties of CD4+ T cells in controlling effector T cell function vs. tolerance to self, and perhaps in controlling anti-cancer immunity." (PMID 32547545, 2020). "Infiltration of naive CD4+ T cells also led to a good outcome in various cancers, whereas that of activated CD4+ T cells (T.cell.CD4.a) indicated poor prognosis in most tumors." (PMID 32714316, 2020). "Based on a handful of identified and validated peptides, it appears clear that cancer patients often display CD4 T cell reactivity against TERT." (PMID 32630460, 2020). "It will be important to determine to what extent these cytokines enhance cancer immunity by improving the function of CD4+ and CD8+ T cells, respectively." (PMID 32708397, 2020). "Generalized linear model showed that old age, comorbidity of malignant tumor, neutrophilia, lymphocytopenia, lower CD4+ T cells, decreased C3 and lower oximetry saturation was positively with the risk of death." (PMID 32746940, 2020). "One consequence of poor antigen presentation would be the absence of the involvement of Th9 cells, which is a subset of CD4 cells that is involved in anti-cancer immunity." (PMID 32483272, 2020). "Endogenous retroviruses are surface expressed and functional targets on cancers, which mean they can be targeted by B-cells and CD4+ T-cells in addition to CD8+ T-cells." (PMID 32650622, 2020). "Cancer cells express various cytokines that inhibit lymphocyte differentiation/proliferation, reduce CD4+ cell levels, and increase CD8%, which further inhibits CD4+ T lymphocytes in a vicious circle." (PMID 32309426, 2020). "High cDC TNBC were significantly associated with a high fraction of anti-cancer immune cells; CD8+ T cells, CD4+ memory T cells, and B cells, and a low fraction of T helper 1 (Th1) in the TCGA cohort (p = 0.038, p < 0.001, and p = 0.004, respectively)." (PMID 33198125, 2020). "Among them, ‘T cells CD4 memory activated’ and ‘Mast cells activated’ were related to the RT outcomes in multiple cancer types." (PMID 32294976, 2020). "TIMER47 is a comprehensive resource for systematic analysis of immune infiltration of different cancer types, which can assess six immune infiltrates (B cells, CD4+ T cells, CD8+ T cells, neutrophils, macrophages, and abundance of dendritic cells)." (PMID 32917854, 2020). "A decreasing trend with advancing cancer stage in terms of CD4+ T‐cell counts (F = 4.359, P = .005) was shown in our study." (PMID 32459060, 2020).
cancer (continued). "As the infiltration of FOXP3 expressing CD4+ T cells and regulatory CD4+ T cells in TM treated tumors was decreased, this likely contributes to TM’s anti-cancer effects in vivo." (PMID 32085796, 2020). "CD8+ T cells, CD4+ Th1 cells, NK cells, B cells, classically activated macrophages (M1), and mature dendritic cells (DCs) contribute to anti-cancer functions." (PMID 33396390, 2020). "CD4 T cells can be beneficial for cancer therapy as they can enhance CD8 T cell-mediated elimination of cancer cells." (PMID 33425916, 2020). "Different lineages derived from CD4+ T cells including Th1, Th2, Th17, regulatory T, and Tr1 cells, have extensive effects in cancer development." (PMID 32677955, 2020). "The future of CD4 T cells as systemic biomarkers of response to PD‐L1/PD‐1 blockade lies on more extensive validation cohorts for distinct cancer types, which is currently under way." (PMID 32648370, 2020). "As our future research direction, we would investigate the direct molecular biological mechanisms of metastatic ACC-specific ceRNAs and the intercellular communication between cancer cells and T cells CD4 memory resting and Macrophages M0." (PMID 32175564, 2020). "As the density of TLS is associated with the presence of CD4+ and CD8+ T cells in tumors, its development is related to a favorable prognosis in cancer patients." (PMID 33251010, 2020). "CD4+ regulatory T cells can directly inhibit cytotoxic T cell activity and these cells can be recruited, or induced, by cancer cells allowing escape from immune attack." (PMID 32299365, 2020). "Both median age and median CD4 count at cancer diagnosis increased between 1996 and 2005 and 2006–2015, in each cancer group." (PMID 32003460, 2020). "This is of high relevance, indicating that the pool of effector and memory CD4+ T cells is fully preserved in cancer patients." (PMID 31973714, 2020). "The results showed that PINK1 was significantly correlated with six different immune infiltrates, B cells, CD8+ T cells, CD4+ T cells, macrophages, neutrophils and dendritic cells, across cancers." (PMID 33244455, 2020). "Several studies have shown that YAP is upregulated in cancer cells, and more recently in the T regulatory (Treg) subset of CD4+ cells." (PMID 32322254, 2020). "Consistently, we observed lower naïve CD4+/CD4+ T‐cell percentages in cancer patients than in controls, suggesting that the immune system was activated against cancer and naïve CD4+ T cells had differentiated into other cell types." (PMID 32459060, 2020). "Genes altered in Yap-cKO TILs were also significantly associated with patient survival across several cancers, as seen most significantly in LUAD for both CD4+ and CD8+ Yap-cKO gene signatures." (PMID 31929526, 2020). "In comparison, cd4, which has a net positive charge of +8 displayed relatively low anti-cancer activity with a LC50 of 5.1 μM and consequently low hemolysis (>40 μM)." (PMID 32153522, 2020). "CTLs fight infections and cancer in vivo in concert with other immune cells, like CD4+ T cells and macrophages." (PMID 32696761, 2020). "SIGLEC family genes were correlated with macrophage, neutrophil, and dendritic cell infiltration in broad cancer types, and in specific tumors, correlation with B cell, CD4+ T cell, and CD8+ T cell infiltration levels were high." (PMID 33240817, 2020). "Their structures were confirmed by NMR, and ESI-MS, and its cytotoxic activity was evaluated in three cancer cell lines and primary CD4+ T cells at different proliferative cycles." (PMID 32326138, 2020). "In contrast, CD4+ Th2 cells, regulatory B cells, CD4+ regulatory T cells (Tregs), myeloid-derived suppressor cells, and alternatively activated macrophages (M2) are pro-cancer immune cells." (PMID 33396390, 2020). "What is more, KLHL5 expression was associated with the immunocyte level of B cell in 21 types, CD8+ T cell in 27 types, CD4+ T cell in 25 types, macrophage in 33 types, dendritic cell in 31 types, and neutrophil in 33 cancer types." (PMID 33363208, 2020).
cancer (continued). "Whereas effector CD4+ and CD8+ T cells promote immune activation and can drive clearance of infections and cancer, CD4+ regulatory T (Treg) cells suppress their function, contributing to both immune homeostasis and cancer immunosuppression." (PMID 33144667, 2020). "There were decreased levels of natural killer (NK) cells, CD8+ T cells, and naïve CD4+/CD4+ T cells in untreated patients with cancer compared to those in healthy controls." (PMID 32459060, 2020). "More importantly, CCR5 is preferentially expressed on CD4+Foxp3+ Tregs over CD4+Foxp3− T-cells in healthy individuals and more so in cancer patients." (PMID 33375291, 2020). "In an article published in 2019 by Cancer Discovery, the authors touch on the importance of naïve CD4+ T cells in pediatric cancer patients receiving immunotherapies." (PMID 33105566, 2020). "High-dose recombinant human IL-2 (aldesleukin) was originally approved as a cancer immunotherapy due to its stimulatory activity on cancer-killing effector CD4+ and CD8+ T cells and NK cells." (PMID 32411127, 2020). "Results showed significant phenotypic changesbetween these two populations when naïve CD4+ Tcells were cultured with normal-ASCs and cancer-ASCs (P=0.017 and 0.008, respectively)." (PMID 31721539, 2020). "CD8 T cells lyse and clear cancer cells directly, but after being primed by CD4 T cells and the crosstalk of these T lymphocytes is part of the cancer immune cycle." (PMID 32971948, 2020). "Our results also revealed that the Lip-DOPE-P5+435 formulation increases subpopulations of CD4+ T cells as a Th1 profile that contribute to the strong antitumor activity against cancer cells." (PMID 33301467, 2020). "VLPs co-administrated with a suitable adjuvant activate DCs, promote their maturation and proper presentation of cancer antigens to CD4+ and CD8+ T cells." (PMID 32582186, 2020). "It was confirmed that the levels and functions of naïve CD4+ T cells were significantly diminished in cancer and HIV patients compared with healthy individuals." (PMID 32459060, 2020). "CD4+ T cells are critical to the establishment of an effective and well-regulated immune response during an infection, as well as during cancer." (PMID 32326073, 2020). "The expression levels of HHLA2, PD-L1, CD8, and CD4 in cancer tissues from cases (206 in the training cohort and 197 in the validation cohort) with surgically resectable primary ccRCC were evaluated by immunohistochemistry." (PMID 31959726, 2020). "As we currently understand normal anti-cancer responses, a functional immune system is a key component that suppresses cancer: Foxp1 controls mature B-cell survival and development, and is a regulator for CD4+ T cells." (PMID 32577159, 2020). "Effects of natural killer cells, circulating lymphocytes, CD8+T cells, and CD4+T cells on cancer cells have been investigated." (PMID 32148558, 2020). "Such an autologous cellular tropism of circulating CD4+ T cell-derived sEVs can have important implications in disease conditions such as cancer and HIV." (PMID 32765528, 2020). "CIBERSORT analyses in two independent cohorts resulted in a positive miR-18a and -18b correlation with CD4+ T-cell memory cells; a subset of T-cells that can recognize foreign invaders such as bacteria or viruses, as well as cancer cells." (PMID 32370743, 2020). "We observed significantly decreased NK‐cell counts, CD8+ T‐cell counts, and naïve CD4+/CD4+ T‐cell percentages in all cancer types compared to healthy controls." (PMID 32459060, 2020). "CD4+ T‐cell counts, and percentages of CD8+ HLA‐DR/CD8+, CD8+ CD38+/CD8+ are associated with the cancer progression." (PMID 32459060, 2020). "Various CD4+ T cells, including regulatory T (Treg) and T helper 17 (Th17) CD4+ T cell have been observed to mechanistically promote tumorigenesis, cancer progression and metastasis through immunosuppressive and pro-inflammatory functions." (PMID 33244455, 2020).
cancer (continued). "Meanwhile, the correlations between PINK1 expression and the infiltration levels of B cells, CD8+ T cells, CD4+ T cells, macrophages, neutrophils and dendritic cells were significant in 13, 15, 20, 23, 15, and 21 cancer types, respectively." (PMID 33244455, 2020). "Increasing numbers of studies highlight the importance of CD4+ CTLs in chronic viral inflammation and cancer immunity." (PMID 32102981, 2020). "Studies have demonstrated that YAP is upregulated in not only cancer cells, but also by the T regulatory (Treg) subset of CD4+ cells." (PMID 32322254, 2020). "In the meantime, cancer immunotherapy strategies have mainly focused on modulating the function of infiltrating CD4+ and CD8+ lymphocytes." (PMID 32448803, 2020). "Recent clinical studies of neoantigen cancer vaccines report similar observations, in which the peptide neoantigen cancer vaccines predominantly induced CD4+ T cells despite the peptides being selected based on MHC class I predictions." (PMID 33298945, 2020). "On the contrary, for non‐HPV‐positive cancer, CD4 count would reflect reduced immune surveillance for malignant cells in the development of HNSCC." (PMID 33094910, 2020). "The populations of CD39+CD73+CD25+FOXP3+and CD39+CD73+CD25-FOXP3+ T lymphocytes werephenotypically compared when naïve CD4+ T cellscultured with cancer-ASCs, normal-ASCs and controlgroup." (PMID 31721539, 2020). "So hypothetically the splicing events identified in our study can generate neoepitopes for CD8+ or CD4+ T cells, cancer immunotherapy targets will be largely expand." (PMID 33046974, 2020). "In both murine models and cancer patients, anti‐CTLA‐4 monotherapy is associated with an expansion of ICOS+ CD4+ Th1 effectors." (PMID 32508018, 2020). "WT1 is widely expressed by many human cancers and contains numerous CD4+ and CD8+ T‐cell epitopes distributed across multiple HLA allotypes." (PMID 32547743, 2020). "Previous studies indicated that the abundance of naive CD4+ T cells is often correlated with poor prognosis of cancer patients." (PMID 32969836, 2020). "NK‐cell counts (P < .001), CD8+ T‐cell counts (P < .001), and naïve CD4+/ CD4+ T‐cell percentages (P < .001) were lower in cancer patients than in healthy controls." (PMID 32459060, 2020). "Initially, CD8+ CTLs and CD4+ T helper cells can limit cancer development by production of IFNγ and cytotoxins, but many mechanisms including an immunosuppressive TME and chronic inflammation can override these effects to promote cancer development." (PMID 32937961, 2020). "In particular, there are 84.38% and 56.25% cancer types with significant difference in CD4 and CD8 T-cell infiltration between the immune-related and all lncRNAs." (PMID 32081859, 2020). "In recent years, clinical observations indicated that CD4+ CD25+ regulatory T cells (Tregs) played a promoting role in various cancers such as gastric, colorectal, pancreatic cancers and hepatocellular carcinoma." (PMID 32677955, 2020). "Accordingly, we observed decreased CD4+ /CD8+ T cell ratios in cancer patients’ PBMCs, suggesting an overall increase in the CD8+ T cell subset in cancer patients when compared to healthy individuals." (PMID 33230147, 2020). "This is reflected by a stronger selective pressure of mutations in MHC-II-restricted neoantigens compared to MHC-I-restricted neoantigens during tumorigenesis, which reinforces the key contribution of CD4 T cells in cancer immunosurveillance." (PMID 33329566, 2020). "In parallel, iron application inhibited the activation, expansion and survival of cytotoxic CD8+ T cells and of CD4+ T helper cells type 1 and significantly reduced the efficacy of the investigated anti-cancer treatments." (PMID 33344239, 2020).